TNF (tumor necrosis factor)
Diseases named in the same sentence as TNF in open-access papers (continued):
Sharing a sentence is not in itself a finding about the gene and the disease.
Obesity (continued). "Regarding inflammatory markers, which were studied since obesity is linked with a chronic low-grade inflammatory state, a moderate decrease in IL-1β levels and a significant decrease in TNF-α levels in participants of the PB group over time were observed." (PMID 35745249, 2022). "Obesity-associated low adropin levels are related to high TNF-α levels, which act on adipocytes decreasing adiponectin mRNA stability and expression, resulting in decreased adiponectin formation." (PMID 35897011, 2022). "Obesity has also been correlated with an increase in low-grade inflammation, which is linked to an increase in tumor necrosis factor-α (TNF-α) and other circulating cytokines." (PMID 35055191, 2022). "Inflammation is one of the critical processes associated with obesity, and the expression of TNF-α, an essential pro-inflammatory cytokine, is elevated in the adipose tissue of several experimental models of obesity." (PMID 35893900, 2022). "The main mechanism by which obesity can cause vascular changes involves perivascular adipose tissue, which can secrete TNF-α and IL-6." (PMID 36013196, 2022). "Among these, the close associated of cytokines with obesity, TNF-α, IL-6 and adiponectin are further introduced." (PMID 35054932, 2022). "Increased levels of maternal CRP and TNF-α, pro-inflammatory cytokines that are elevated in mothers with obesity, have been associated with wheezing and lower respiratory tract infections in offspring." (PMID 36189369, 2022). "It was inferred that the A/A genotype (recessive model) of the TNF gene (rs1800629) was associated with a high risk of presenting an obesity phenotype (OR = 10.29, 95% CI 1.22–86.59, p = 0.0081)." (PMID 35207726, 2022). "TNF‐deficient obese mice are protected from obesity‐induced insulin resistance in muscle and adipose tissues." (PMID 36119080, 2022). "Increased TNF also promotes tumor cell growth, proliferation, angiogenesis, invasion and metastasis helps explain why obesity increases the risk of cancer." (PMID 37990728, 2022). "Obesity is associated with low-grade inflammation characterized by an increased production of proinflammatory cytokines, such as tumor necrosis factor-α (TNF-α), interleukin-1β (IL-1β), and interleukin-6 (IL-6)." (PMID 36235574, 2022). "The association between TNF-alpha and other surrogate markers of inflammation such as c-reactive protein is also strengthened obesity in GDM." (PMID 36992779, 2022). "As natural compounds, these hydroxycinnamic derivatives were shown to protect against obesity associated health complications by targeting the proinflammatory tumor necrosis factor (TNF-α) and nuclear factor κB (NF-κB) pathways via reducing their expression." (PMID 35663953, 2022). "Regarding the effect of vitamin D on obesity-associated inflammation, increased serum concentrations of inflammatory cytokines, such as IL-6 and TNFα, have been reported in obese subjects with a vitamin D deficiency." (PMID 36142842, 2022). "In both human and animal models, diet-induced obesity is associated with increased circulating inflammatory markers such as TNF-α, IL-1β, and IL-6, which represent a key step in the development of insulin resistance in peripheral organs." (PMID 35871167, 2022). "Recent studies showed that obesity caused by a fatty diet increases the serum levels and intestinal expression of proinflammatory cytokines such as IL-6 and TNF-α, which are also key to the course of IBD." (PMID 36364889, 2022). "Three studies evaluated skin fragility associated with obesity and surface TNF‐α level, suggesting this represents a possible test of skin's mechanical vulnerability in obese patients." (PMID 35638724, 2022). "CRP, IL-6, TNFα, and leptin are found to be elevated in individuals with obesity and are also strongly associated with the development of preeclampsia." (PMID 35348641, 2022). "In the early 1990s, it was first identified that obesity was associated with increased TNF-α expression in adipose tissue of obese mice." (PMID 35941819, 2022).
Obesity (continued). "Administering BMS-303141 attenuated the inflammatory cell recruitment and pro-inflammatory factor monocyte chemoattractant protein-1 (MCP-1), and TNF-α, the key inflammatory factor in obesity-associated inflammation." (PMID 36568100, 2022). "In a previous study, it was shown that TNF-α and IL-6 were associated with obesity or insulin resistance." (PMID 35737354, 2022). "Our data were also compatible with previous publications, which reported increased circulating levels of TNF-α associated with obesity not only in rodents but also in obese patients." (PMID 35206342, 2022). "Elevated TNF-α levels are associated with a variety of conditions, including obesity and depression." (PMID 36387880, 2022). "In our analysis, IL-17 displayed a stronger association than TNF-α with the degree of insulin resistance in our cohort of children with obesity, and thus was the focus of our study." (PMID 35305128, 2022). "Obesity is characterized by high levels of several proinflammatory markers, including IL-6 and TNF-α, that cause chronic low-grade inflammation." (PMID 35336365, 2022). "On the other hand, inflammatory biomarkers hsCRP, IL-6, and TNF-alpha are associated with obesity and other diseases, including inflammation, infection, heart attack risk, and cancer." (PMID 35053667, 2022). "This polymorphism and obesity predicted a poor response to TNF-α blockers, which makes the selection of the right therapy for psoriasis even more difficult in terms of muscle mass, fat mass, other risk factors and other variables." (PMID 35330186, 2022). "Cytokines such as leptin, adiponectin, and TNF produced by adipocytes have been shown to be associated with obesity and osteoarthritis." (PMID 36568091, 2022). "Chronic low-grade inflammation, present in obesity and favored by it, causes decreased muscle anabolic function, which is mediated by variations in the production of factors such as TNF, IL-6, leptin and GH." (PMID 35326591, 2022). "We additionally reviewed a number of studies reporting the levels of TNF-α across the different genotypes for other variants associated with different genes related with obesity and metabolic disorders." (PMID 36010524, 2022). "Yet, high levels of tumor necrosis factor-α (TNF-α), interleukin-6 (IL-6), adiponectin and angiotensin II and dysregulated metabolites are associated with obesity-induced kidney injury." (PMID 35054932, 2022). "Obesity, as a component of MS, is associated with chronic inflammatory state due to the production of proinflammatory cytokines, such as TNF-α and IL-6." (PMID 35223684, 2022). "Individuals with obesity have higher circulating lipopolysaccharide (LPS) levels associated with elevated pro-inflammatory cytokines TNF-α and IL-6 expression." (PMID 35579462, 2022). "The decrease of TNF-α and IL-6 can alleviate insulin resistance and liver steatosis caused by obesity." (PMID 36079890, 2022). "Increased levels of IL-6, CRP and TNF-α are present in children with obesity, which increases atherosclerotic risk factors." (PMID 36292751, 2022). "It is documented that aortic tissues from obese Zucker rats showed an increased expression of TNF-α in vascular tissue, indicating that obesity is associated with vascular inflammation." (PMID 35206342, 2022). "Intriguingly, TNF-α mediates endothelial cell apoptosis, possibly influencing atherosclerosis, an obesity-associated comorbidity." (PMID 35631100, 2022). "The response to TNF inhibitors (TNFi) is particularly influenced by BMI: in a meta-analysis including 22 cohorts with PsD, obesity was associated with poor response to TNFi in obese patients (OR for failing to respond to TNFi: 1.57 [1.30-1.89])." (PMID 36159785, 2022). "Several studies have shown that obesity-associated inflammation stimulates pro-inflammatory cytokines such as TNF-α or Interleukin-1, which can trigger EMT in the epithelial cells." (PMID 36568100, 2022).
Obesity (continued). "Obesity raises the adipokine tumor necrosis factor-α (TNF-α), which causes the development of insulin resistance as well as diabetes." (PMID 35983376, 2022). "It is now also clear that TNF-α has an impact on healthy metabolism as well as on metabolic diseases, particularly, on obesity-linked glucose metabolism and insulin resistance (IR)." (PMID 36010524, 2022). "The secretion of adipokines (leptin and adiponectin) and cytokines (C-reactive protein, TNF, IL-6, IL-8) driven by adipose tissue in obesity can alter the expression and secretion of factors associated with angiogenesis in the primary tumor." (PMID 36014894, 2022). "In patients with COVID-19 and obesity, high serum levels of IL-6 and TNF-α are negatively associated with T cells." (PMID 36615820, 2022). "First, the effects of the obesity-related molecule TNFα and the insulin-sensitizer AdipoRon on molecules associated with the adiponectin signaling pathway in the in vitro model were evaluated." (PMID 35409282, 2022). "Logistic analysis revealed that after adjusting for sex, age, hypertension, obesity, as well as IL-10, IL-4, and IL-6, an increased plasma level of TNF-α was significantly associated with sarcopenia (P < 0.001)." (PMID 36160136, 2022). "These suggest that adipokines play an integral role in the development of obesity-induced kidney damage —for example, elevated levels of TNF-α, and IL-6 are associated with a more accelerated progression of CKD." (PMID 35054932, 2022). "Adipose tissue is a major source of pro-inflammatory and anti-inflammatory factors In obesity, excess adipose tissue causes an increased production of pro-inflammatory factors such as tumor necrosis factor (TNF-α), interleukin (IL)-6, IL-1β, and resistin." (PMID 35885049, 2022). "It has also been shown that obesity is associated with increased levels of inflammation-promoting cytokines such as tumor necrosis factor (TNF-), which is associated with decreased expression of perilipin A in obese people's adipose tissue." (PMID 36503541, 2022). "Obesity is associated with low adropin levels and high TNF-α levels which inhibit LH production and decrease total testosterone levels." (PMID 35897011, 2022). "The expression of inflammatory markers as CD68, IL-6, TNFα and lysozyme is increased during obesity and associated with insulin resistance." (PMID 36432612, 2022). "Tumor necrosis factor-alpha (TNF-α) is a pro-inflammatory cytokine that modifies adipose tissue function, influences adipogenesis and is involved in complications associated with obesity." (PMID 36005598, 2022). "Sankey plot analysis connected a total of 25 miRNAs that are known to be regulators of canonical inflammatory genes involved in obesity, such as TNF-α, IL-6, and IL-1β, to the list of L_Ag-associated DEMs and O_Ag-associated DEMs." (PMID 35798800, 2022). "Risk factors for the development of OA include age, obesity, physical injury, and low-grade systemic inflammation where pro-inflammatory mediators such as IL-6 and TNFα can exacerbate cartilage erosion." (PMID 36227956, 2022). "Increased TNF-α expression has been observed in adipose tissue of obese rodents and human subjects contributing to obesity-associated insulin resistance and hence the development of T2DM." (PMID 35083338, 2022). "Regarding the association between TNFRSF13B, TNFRSF10A, and type II diabetes mellitus, our results support previous findings of TNF-α being linked to obesity and insulin resistance." (PMID 35211520, 2022). "Obesity has been associated with lower TNF inhibitor levels also in RA patients and lower clinical response in patients with rheumatic diseases using TNF inhibitors." (PMID 34357455, 2022). "The high increase in TNF-α is associated with obesity and IR, through the up-regulation of SOCS3 (suppressor of cytokine signaling 3)." (PMID 35008925, 2022).
Obesity (continued). "We additionally explore the influence of different single nucleotide polymorphisms (SNPs) on TNF-α levels and compare the response to food products with that to some anti-obesity drugs." (PMID 36010524, 2022). "Pro-inflammatory cytokines such as IL-1β, IL-6, and TNF-α closely interact with immune and metabolism regulatory systems and modulate the risk for diabetes mellitus type II and obesity." (PMID 35206947, 2022). "In terms of obesity and obesity-related factors, MR analysis and other studies on the effects of adiponectin, leptin and TNF on EC risk have obtained different results." (PMID 35615721, 2022). "The state of inflammation in obesity is associated with adipose tissue dysfunction, which increases the secretion of pro-inflammatory cytokines such as TNF-α, CRP, and IL-6." (PMID 35740977, 2022). "It has been reported that exercise causes blood inflammatory cytokine levels to rise, that regular exercise suppresses TNF-alpha and that obesity and ageing are associated with the elevation of blood inflammatory cytokine levels." (PMID 35887537, 2022). "TNFα is associated with obesity and insulin resistance, and is also known as an activator of NFκB-driven inflammation by binding to TNFR134,56,57." (PMID 36496443, 2022). "Obesity is associated with chronic low-grade systemic inflammation and the secretion of proinflammatory cytokines (TNF-α, IL-6, and IL-8) by adipocytes or adipose tissue-infiltrating immune cells." (PMID 35887932, 2022). "Increased levels of TNF-α have been linked with obesity and the associated low-grade chronic inflammatory status as well as with the derived cardiometabolic disorders." (PMID 36010524, 2022). "Obesity is usually associated with an increase in inflammation, and high in situ levels of IL-6 and TNFα, which can aggravate liver injury and weaken the hepatic glucolipid and lipid metabolism." (PMID 35382381, 2022). "At the molecular level, obesity is associated with impaired Akt activity, enhanced NF-κB and FoxO1, and increased TNF-α and IL-6 levels, all of which are related to muscle atrophy." (PMID 35010979, 2021). "Scientific evidence suggests that obesity, in particular chronic visceral adiposity, is associated with inflammatory markers including interleukin-6 (IL-6) and tumor necrosis factor-alpha (TNF-α)." (PMID 34938803, 2021). "Low sTWEAK concentrations were associated with more inadequate cardiometabolic risk in patients with type 2 diabetes and obesity, and this can be explained by the ability of sTWEAK to antagonize in vitro TNF-α activity." (PMID 34764367, 2021). "Studies have confirmed that insufficient sleep is associated with increases in tumor necrosis factor, interleukin 6 and C-reactive protein, which play important roles in obesity." (PMID 34952580, 2021). "Obesity is associated with overproduction of leptin, leading to leptin-induced local and peripheral inflammation via the activation of TNF-α and IL-6 production, and stimulation of surface markers." (PMID 34844584, 2021). "So far, studies point towards a pro-tumorigenic role for most of the obesity-associated cytokines, whereof some, i.e., TNF-α, IL-6, and IL-10, also seem to induce activities inhibiting tumor progression." (PMID 34944905, 2021). "Obesity is associated with macrophage activation and production of pro-inflammatory cytokines including TNF-α, IL-1b, and IL-6." (PMID 34970568, 2021). "The second reason involves inflammatory factor stimulation, as obesity can cause adipose cells to secrete inflammatory factors, such as C-reactive protein, interleukin 6 (IL-6), IL-10, and tumor necrosis factor (TNF-α)." (PMID 35004287, 2021). "It is especially remarkable how both compounds are capable of reducing insulin resistance by lowering glycemia and plasma insulin concentrations as well as obesity-associated inflammatory markers such as IL-6 and TNF-α." (PMID 34444748, 2021).
Obesity (continued). "In particular, the excessive secretion of inflammatory cytokines, including TNF-α, and suppression of anti-inflammatory cytokines from abnormal adipocytes are the potential mechanisms underlying obesity-induced inflammation and endothelial dysfunction." (PMID 34641407, 2021). "Obesity predisposes patients to a pro-inflammatory state via increased inflammatory mediators interleukin-6 (IL-6) and tumor necrosis factor-α (TNF-α), as well as reduced levels of adiponectin, which has a totally anti-inflammatory function." (PMID 33919190, 2021). "According to Bianchi, testosterone is immunoregulatory by suppressing the synthesis and proliferation of pro-inflammatory cytokines, such as TNF-alpha, thereby reducing the risk of obesity, atherosclerosis, and metabolic syndrome." (PMID 34667891, 2021). "On the one hand, IRE1α promotes the activation of an obesity-associated inhibitor of the NFκB pathway, leading to the production of typical pro-inflammatory cytokines such as TNF and IL-6 in the liver." (PMID 33897888, 2021). "Increased secretion of proinflammatory cytokines, such as tumor necrosis factor-alpha (TNFα), is often associated with adipose tissue dysregulation, which often accompanies obesity." (PMID 34576943, 2021). "For instance, knockout animal studies have implicated pro-inflammatory cytokines, such as IL-6 and TNF-α, in the development of obesity." (PMID 34063221, 2021). "TNF-α is a classic proinflammatory factor that causes hypothalamic insulin and leptin resistance and is believed to be a contributor to the development of obesity." (PMID 34275474, 2021). "Obesity stimulates the adipose tissues to release inflammatory mediators such as tumor necrosis factor α and interleukin 6, predisposing them to a proinflammatory state and oxidative stress." (PMID 34573003, 2021). "Elevation in the levels of TNF-α secreted by adipocytes in patients with obesity is associated with insulin resistance-induced impaired glycemic control." (PMID 34641407, 2021). "Accumulating studies show elevated levels of plasma TNF-α and IL-6 in patients with obesity associated insulin resistance." (PMID 33917607, 2021). "The obesity skewed immune responsiveness, which broadly favors proinflammatory cytokine (e.g., IL-6, TNF) and chemokine (e.g., CCL2) production, is directly linked with obesity-driven metabolic derangements." (PMID 34099626, 2021). "Regarding the obesity status, independent associations were found only for TNF-α and CCR2 with SRA1 expression in NW (n = 12), and overweight (n = 32) participants." (PMID 34685582, 2021). "Pregravid obesity disrupted pregnancy-associated monocyte activation, leading to a significantly reduced number of TNFα/IL-6 producing monocytes relative to lean subjects in response to LPS at T3." (PMID 34195568, 2021). "Chicoric acid was found to reduce lipid peroxidation and increase the antioxidants activity and TAC in liver of mice and prevent inflammations of hepatic cells associated with obesity via decreasing the IL-6, TNF-α, and MPO activity." (PMID 34827094, 2021). "In particular, the insulin resistance featuring obesity has been related to the low grade chronic inflammation which, in turn, associates with the overexpression of TNF-α in adipose tissue." (PMID 34539566, 2021). "The association between a high level of TNFα and obesity/lipodystrophy suggests a role of TNFα in inducing apoptosis." (PMID 33872596, 2021). "CRP (C-reactive Protein) and TNF alpha, two inflammatory markers commonly associated with low grade inflammation in obesity, were significantly lower in the IP group versus CP group (p < 0.05 and p < 0.01 respectively)." (PMID 34341379, 2021). "2KB upstream variants rs1800630 A and rs1799964 C of the TNF gene predispose Sian Indians to obesity." (PMID 34834553, 2021).